CXCL9 (C-X-C motif chemokine ligand 9)
Diseases named in the same sentence as CXCL9 in open-access papers (continued):
Sharing a sentence is not in itself a finding about the gene and the disease.
ovarian carcinoma (60 papers, 2013 to 2026). A malignant neoplasm originating from the surface ovarian epithelium. "CXCL9 has been confirmed to be associated with ovarian cancer prognosis; it is related to the survival rate of patients with high-grade serous ovarian cancer (HGSC) and is an independent marker of good prognosis in HGSC patients." (PMID 39680618, 2024). "Overexpression of CXCL9 has been reported to associate with increased T-cell infiltration and prolonged OS in ovarian cancer." (PMID 36845675, 2023). "Improved survival, a preferable anti-PD-L1 therapy caused by the overexpression of CXCL9 in ovarian cancer, determined it as a stable predictive target." (PMID 36704336, 2022). "In ovarian cancer, high IHC expression (measured on a 0–3 scale) of the tumour cell CXCL9 was associated with doubled overall survival rates." (PMID 34830795, 2021). "Elevated CXCL9 expression is associated with improved survival in patients with ovarian cancer." (PMID 37525619, 2023). "Moreover, in an attempt to decipher genes associated with tumour regression and therapy response, CXCL9 emerged once again as the most upregulated gene in regressive, chemosensitive metastases of ovarian cancer patients." (PMID 35314795, 2022). "For MIG (CXLC9), the negative association between patient survival time and FC may seem surprising in view of the fact that CXCL9 up-regulation has been linked to improved survival in patients with other common cancer types, including breast and ovarian cancer." (PMID 31355141, 2019). "CXCL9 overexpression results in T cell accumulation and improved survival in ovarian cancer, acting as a predictive biomarker." (PMID 39770478, 2024). "The same is true for ovarian cancer, where preclinical models have demonstrated a positive correlation between CXCL9 expression and T cell infiltration and overall survival." (PMID 37644593, 2023). "The radiomics-based nomogram, which incorporates clinical and CT characteristics, can predict CXCL9 status in a noninvasive manner, potentially fulfilling the ultimate purpose of precision medicine for ovarian cancer." (PMID 37644593, 2023). "Macrophages promoted the expression of CXC chemokine ligand 9 (CXCL9) and M1 phenotype via activating the NF-κB signaling pathway, thereby increasing cytotoxic T cell infiltration, and inhibiting the progression of epithelial ovarian cancer." (PMID 37386521, 2023). "Based on the evidence of human samples and C57BL/6 mouse assay, hyper-expressed CXCL9 has been proven to stifle tumor cell growth and promote anti-PD-L1 therapy in ovarian cancer, especially the histological subtypes of clear-cell carcinomas." (PMID 36845675, 2023). "We developed a radiomic model to identify CXCL9 status in ovarian cancer (OC) and evaluated its prognostic significance." (PMID 37644593, 2023). "Increased levels of the chemokines CXCL9, CXCL10, CXCL11, and CCL5 are all associated with an immune-reactive ovarian cancer microenvironment and improved patient prognosis." (PMID 35131874, 2022). "Our study provides evidence for a central role of this chemokine in ovarian cancer immune intervention and renders CXCL9 a promising predictor and driver of ICB response in this cancer entity." (PMID 35314795, 2022). "When melanoma or ovarian cancer cells overexpressing CXCL9 are s.c. injected into mice, the CD4 and CD8 T-cell recruitment and activation are increased and the tumor growth is slowed down." (PMID 36429101, 2022). "The moderate correlation of PD-L1 and CXCL9 expression in human ovarian cancers most likely represents a consequence of interferon response in these tumours." (PMID 35314795, 2022). "We previously identified high CXCL9 expression as a strong prognostic favourable marker in high-grade serous ovarian cancer, which was confirmed in several genomic studies on ovarian cancer." (PMID 35314795, 2022).
ovarian carcinoma (continued). "In conclusion, our study provides a functional basis for the protective nature of the CXCL9 chemokine and identifies it as a sufficient driver of successful immune checkpoint blockade in ovarian cancer." (PMID 35314795, 2022). "Expanding prior reports already suggesting involvement of CXCR3 chemokines in the ICB mechanism of action, our study is, to the best of our knowledge, the first to demonstrate that CXCL9 is all by itself sufficient to overcome ICB resistance in ovarian cancer." (PMID 35314795, 2022). "Several unsupervised studies, aiming to define the molecular subtypes of ovarian cancer by gene expression profiling, univocally identified CXCL9 and the other CXCR3 chemokines as marker genes of an inflammation-enriched subtype." (PMID 35314795, 2022). "Onset of ascites, indicated by visible abdominal swelling and one of the cardinal symptoms in ovarian cancer patients, was significantly delayed in Cxcl9+ tumour-bearing hosts compared to the Control group (median 53 vs. 39 days; P = 0.002)." (PMID 35314795, 2022). "In ovarian cancer, CXCL9 overexpression has been shown to correlate with enhanced T-cell infiltration and improved overall survival." (PMID 35314795, 2022). "Despite this considerable evidence indicative of a crucial role of CXCL9 in ovarian cancer biology, its actual function therein has been poorly investigated." (PMID 35314795, 2022). "Several studies have identified the chemokine CXCL9 as a robust prognosticator of improved survival in ovarian cancer and a characteristic of the immunoreactive subtype, which predicts ICB response." (PMID 35314795, 2022). "Through the pROC package analysis, we observed that CXCL10 showed a predictive advantage in the infiltration group when compared to CXCL9 in four independent groups of ovarian cancer (left)." (PMID 34386037, 2021). "In this large-scale multi-platform study of 10 microarray datasets consisting of 1,673 ovarian cancer patients, we comprehensively evaluated CXCL10 and CXCL9 expression risk classifications for predicting overall survival (OS) and TME immune characteristics." (PMID 34386037, 2021). "In line with this, our results observed that CXCL10 played a prior role in ovarian cancer immune characteristics and progress when compared to CXCL9." (PMID 34386037, 2021). "The CXCL10 and CXCL9 expression levels showed a positive correlation in four independent groups of ovarian cancer." (PMID 34386037, 2021). "In patients with ovarian cancer, IL-17 derived from Th17 cells has been shown to induce the production of CXCL9 and CXCL10 by tumor cells and tumor infiltrated macrophages, which recruits CXCR3-expressing CTLs and NK cells into tumor tissues." (PMID 34885241, 2021). "CXCL9 has recently been identified as a critical mediator of anti-tumor T cell responses, and high CXCL9 levels are associated with increased numbers of CD8 positive T cells in ascites and better prognosis in ovarian cancer patients." (PMID 33028251, 2020). "Combined with the results in ovarian cancer, we surmise that CXCL9 and CXCL10 exert tumor-suppressive function by TIL recruitment through the JAK/STAT and NF-κB pathways." (PMID 32963527, 2020). "In contrast, in ovarian cancer, high CXCL9 and CXCL10 expression doubled the overall survival time due to improved recruitment of tumor-infiltrating lymphocytes." (PMID 30319622, 2018). "Interestingly, anti–PD-L1 treatment was found to act synergistically with CXCL9 overexpression in the ovarian cancer model, resulting in a significantly prolonged time to onset of ascites and prolonged overall survival." (PMID 40673486, 2025). "CD6, CXCL9, and CXCL13 were associated with favorable outcomes in BRCA1-mutant ovarian cancers." (PMID 40647506, 2025).
ovarian carcinoma (continued). "Its function in ovarian cancer has been much less studied than that of CXCL9 or CXCL10." (PMID 39862711, 2025). "Interestingly, in this study, we also discovered that ovarian cancer cells with high GBP5 expression exhibit increased expressions of CXCL9/10/11 in a co-culture assay." (PMID 38817865, 2024). "Ovarian cancer studies had shown that CXCL9 overexpression could result in T cell accumulation and prolonged survival, and thus, have important synergistic roles in ICB." (PMID 38957805, 2024). "Recent studies on gastric cancer and ovarian cancer have also shown that CXCL9 could enhance or reverse resistance to immunotherapy related to the PD-1/PD-L1 axis." (PMID 38957805, 2024). "PSMA2 overexpression is observed in ovarian cancer, and chemokine ligand 9 (CXCL9) is a vascular inhibitor that could inhibit ovarian cancer through lymphocyte invasion." (PMID 38481252, 2024). "CXCL9 is a driver of successful ICB in preclinical ovarian cancer." (PMID 35314795, 2022). "Next, we asked what mechanism drives Cxcl9-mediated tumour suppression in ovarian cancer." (PMID 35314795, 2022). "We reasoned that pharmacologic approaches to activate the CXCR3/CXCL9–11 pathway might be of therapeutic benefit in ovarian cancer." (PMID 35131874, 2022). "To test whether this may be due to a higher proportion of CXCL9-high tumours in this histological subtype, we now evaluated CXCL9 expression in a cohort of other histological subtypes of ovarian cancer." (PMID 35314795, 2022). "However, our in vivo results of CXCL9 promoting ICB efficacy in ovarian cancer fuel this assumption." (PMID 35314795, 2022). "CXCL9 expression analysis in ovarian cancer subtypes and correlation to reported ICB response." (PMID 35314795, 2022). "Next, we set out to test the hypothesis that CXCL9 improves anti-PD-L1 treatment in BRCAWT ovarian cancers due to an upregulation of PD-L1." (PMID 35314795, 2022). "In this study, based on visual inspection curves of estimated survival dependent on CXCL10 and CXCL9 expression, we integrated multiple datasets with gene expression, which contained 1,673 cases in total to explore ovarian cancer TME immunological characteristics from immune signature gene sets." (PMID 34386037, 2021). "However, it is important to note that a variety of human tumours, including for example breast, colon and ovarian cancers, express CXCL9/10/11 or do so after chemotherapy." (PMID 31803974, 2020). "In high-grade ovarian cancer, a study reported intratumoral accumulation of CXCL9 could act as tumor suppressor by significantly improving TIL-dependent immune intervention." (PMID 32974144, 2020). "Thus, in contrast to its favourable prognostic role in other cancer entities and in contrast to the positive prognostic impact of other T-cell and NK cell recruiting chemokines (e.g. CXCL9 and CXCL10) in ovarian cancer, elevated CX3CL1 levels are associated with worsened outcome in HGSOC." (PMID 39862711, 2025). "Ovarian cancer studies have shown that CXCL9 could indirectly impact the upregulation of PD-L1." (PMID 38957805, 2024). "In its capacity as a driver of ICB response, CXCL9 might as well be a predictive biomarker to identify the hitherto small number of ovarian cancer patients that showed durable responses under ICB monotherapy, as PD-L1 expression was shown not to predict therapy response satisfactorily." (PMID 35314795, 2022). "However, the function of CXCL9 in ovarian cancer has been poorly studied." (PMID 35314795, 2022). "Thus, activation of the adaptive immune response seems to be the major mechanism behind the protective nature of CXCL9 in ovarian cancer, possibly more important than chemotactic retention of CXCR3-positive tumour cells in the primary tumour as proposed before." (PMID 35314795, 2022). "Thus, CXCL10 presented a prior role in ovarian cancer when compared to CXCL9." (PMID 34386037, 2021).
ovarian carcinoma (continued). "This study also showed that CXCL9 protein secretion occurred from ovarian cancer cell lines after the addition of IFNG and TNFA using cell culture, which is substantiated by our findings that CXCL9 as well as AIM2 are target genes for IFNG." (PMID 40492347, 2025). "In tubo‐ovarian cancer, interactions between IFN‐Mac_CXCL9 and T/NK cells were mediated by CXCL9/10/11–CXCR3 and CCL3–CCR5 interactions, with similar pattern observed in cervical cancer." (PMID 41275425, 2025). "In a syngeneic mouse model of ovarian cancer, the number of intratumoral CD8+ cells was increased 2.5-fold following CXCL9 overexpression." (PMID 40673486, 2025). "Treatment of mice with EZH2 inhibitor, 3-Deazaneplanocin A (DZNep) or DAC reversed this repression of CXCL9 and CXCL10 and improved responses to CD8+ T cell therapy in an ovarian cancer model." (PMID 41154396, 2025). "For instance, in BRCA1-mut ovarian cancer, KTR14, KRT16, CXCL9, and CFD were highly upregulated (more than 4-fold change), and in BRCA2-mut ovarian cancers, TSPAN7 and CDKN2C were clearly upregulated (more than 2-fold change)." (PMID 40647506, 2025). "Furthermore, high expression levels of CXCL9 and CCL5 were associated with an increased number of tumor-infiltrating CD8+ T cells and better outcomes after PD-1 inhibition in not only patients with ovarian cancer, but also those with other cancers, including colon, lung, and breast cancer." (PMID 37046033, 2023). "Univariate Cox analysis demonstrated that CXCL9, CXCL10, CXCL11, and CXCL13 were protective factors in ovarian cancer (HR < 1, p < 0.01)." (PMID 38054797, 2023). "A study indicates that EZH2 inhibits chemokines, such as CXCL9 and CXCL10, thus impairing the trafficking for CD8+ T cells in human ovarian carcinoma." (PMID 35911718, 2022). "In this study, we carried out an analysis of 1,673 ovarian cancer patients from 10 valid studies and identified the expression patterns of CXCL10 and CXCL9 together with their related TME immune characteristics." (PMID 34386037, 2021). "Our results showed that CXCL1, CXCL8, CXCL9, CXCL11, CXCL12, CXCL16, and CXCL17 were remarkably elevated in ovarian cancer compared to those in normal tissue." (PMID 33763130, 2021). "It has also been reported that the expression of CXCL9, CXCL10, and CXCL11 is upregulated in the tumor tissues of patients with colon cancer, esophageal cancer, lung cancer, and ovarian cancer, and correlates with better clinical outcomes." (PMID 34885241, 2021). "Meanwhile, the chemokine landscape of ovarian cancer was found to be quite heterogeneous, because of different functions of known lymphocyte-recruiting chemokines in TME, such as CCL2, CXCL9, CXCL10, CXCL12, and CXCL16." (PMID 34386037, 2021). "Recently, therapeutic modulators that induce CXCL10 and CXCL9 expression were reported to improve immune cell responses and TME in ovarian cancer." (PMID 34386037, 2021). "For instance, T cell-recruiting chemokines CXCL9, CXCL10, and CXCL11 are favorable prognostic indicators in ovarian cancer, but are unfavorable indicators for pancreatic and renal cancer." (PMID 30873179, 2019). "Although human Th17 cells have no direct cytotoxic effect on cancer cells, Th17 cell-derived IL-17 and IFN-γ synergistically induce CXCL9 and CXC10 production in ovarian cancer, which in turn leads to recruitment of Th1-type effector T cells." (PMID 23565248, 2013). "For instance, trimethylation at H3K27 represses the production of CXCL9 and CXCL10 in ovarian cancer, establishing an immune-suppressive TME, while DNMT1 is responsible for the decreased CXCL12 in osteosarcomas, resulting in reduced CTL recruitment at the cancer site." (PMID 39000359, 2024).
ovarian carcinoma (continued). "However, IL-17 has also been demonstrated to induce the secretion of CXCL9 and CXCL10, which in turn recruited effector CTL and NK cells to inhibit ovarian cancer." (PMID 39906741, 2024). "Promoted the production of blood vessels and inhibited CXCL9 and CXCL10 in ovarian cancer cells." (PMID 39906741, 2024). "The results suggest that both peripheral blood markers and TICs can be used as prognostic predictors in patients with ovarian cancer, and CXCL9, CD79A, MS4A1, and MZB1 may be potential therapeutic targets for ovarian cancer immunotherapy." (PMID 36645174, 2023). "Thus, we also examined CXCL9, CXCL10, CXCL11 in the ovarian cancer cell lines, ES2 and SKOV3, that overexpress ISG20, and found that CXCL10 and CXCL11 were significantly upregulated." (PMID 37342328, 2023). "EOC patients showed higher levels of proinflammatory cytokines (IL-6, TNF-α, and IL-12), regulatory cytokines (IL-10), and chemokines (CXCL-9 and CXCL-10), which corroborated this environmental proinflammatory/regulatory mechanism for the development of ovarian cancer." (PMID 38141599, 2023). "Finally, the CXCR3-positive human ovarian cancer cell lines OVCAR-3, OV-MZ-6, CAOV-3 and SKOV-3 were treated with 100 ng/mL recombinant human CXCL9 for 72 h and lysed for western blot analysis." (PMID 35314795, 2022). "For instance, treatment of ovarian cancer cells with epigenetic modifiers reversed the EZH2 and DNMT1 suppression of expression of the CXCR3 ligands, CXCL9, and CXCL10, resulting in T cell influx into the tumor and improved response to T cell transfer and anti-PD-L1 blockade therapy." (PMID 30873179, 2019). "In contrast, high CXCL9, CXCL10, and CXCL11 expression in the TME of patients with colorectal, oesophageal, non-small cell lung (NSCL) and ovarian cancer is an indicator of improved overall survival, while it is a poor prognostic marker in patients with localized clear-cell RCC." (PMID 30319622, 2018). "In ovarian cancer cell lines, inhibition of EZH2 using DZNep (inhibitor of SAM dependent enzymes), EPZ6438 and GSK126 (selective inhibitor of EZH2) and DNMT (azacytadine) synergistically increase IFN-γ responsiveness, and CXCL9 and CXCL10 expression, while shrinking tumor size." (PMID 34163486, 2021).